ABRAXAS1 (abraxas 1, BRCA1 A complex subunit)
Description:
Involved in DNA damage response and double-strand break (DSB) repair. Component of the BRCA1-A complex, acting as a central scaffold protein that assembles the various components of the complex and mediates the recruitment of BRCA1. The BRCA1-A complex specifically recognizes 'Lys-63'-linked ubiquitinated histones H2A and H2AX at DNA lesion sites, leading to target the BRCA1-BARD1 heterodimer to sites of DNA damage at DSBs. This complex also possesses deubiquitinase activity that specifically removes 'Lys-63'-linked ubiquitin on histones H2A and H2AX.
Synonyms: ABRA1; CCDC98; FAM175A; FLJ13614; ABRAXAS
Tractability: PROTAC: ubiquitination databases record sites on it.
Gene: Protein-coding gene on chromosome 4 (83,459,517 to 83,523,348, reverse strand). Ensembl gene ENSG00000163322.
Subcellular location: Nucleus
Subcellular location (Human Protein Atlas): Nuclear bodies
Pathways (Reactome):
DNA Repair: Nonhomologous End-Joining (NHEJ); Processing of DNA double-strand break ends; Recruitment and ATM-mediated phosphorylation of repair and signaling proteins at DNA double strand breaks
Cell Cycle: G2/M DNA damage checkpoint
Metabolism of proteins: Metalloprotease DUBs
Gene Ontology:
Molecular function: polyubiquitin modification-dependent protein binding; protein binding; microtubule binding
Biological process: double-strand break repair; mitotic G2 DNA damage checkpoint signaling; positive regulation of DNA repair; response to ionizing radiation; attachment of spindle microtubules to kinetochore; mitotic G2/M transition checkpoint; mitotic spindle assembly; regulation of DNA repair
Cellular component: BRCA1-A complex; nuclear body; nucleus; nucleoplasm
Genetic constraint (gnomAD): Loss-of-function variants: 14 observed, 16.24 expected, observed/expected ratio (o/e) 0.86, 90% interval 0.57 to 1.35. The upper end of that interval is the gene's LOEUF score, 1.35, which puts it in group 5 of 6, group 1 being the genes least tolerant of losing a copy. Missense variants: 324 observed, 338.85 expected, observed/expected ratio (o/e) 0.96, 90% interval 0.87 to 1.05. Synonymous variants: 110 observed, 121.26 expected, observed/expected ratio (o/e) 0.91, 90% interval 0.78 to 1.06.
Homologues: Orthologues: chimpanzee ABRAXAS1 (99% identical), macaque ABRAXAS1 (98% identical), dog ABRAXAS1 (86% identical), pig ABRAXAS1 (84% identical), rabbit ABRAXAS1 (82% identical), mouse Abraxas1 (72% identical), rat Abraxas1 (71% identical), guinea pig ABRAXAS1 (64% identical), tropical clawed frog abraxas1 (54% identical), zebrafish abraxas1 (35% identical). Paralogues in human: ABRAXAS2 (29% identical).
Diseases named in the same sentence as ABRAXAS1 in open-access papers:
ABRAXAS1 is named in the same sentence as 14 diseases in open-access papers, as found by Europe PMC text mining. Sharing a sentence is not in itself a finding about the gene and the disease. The quoted sentences say what the papers report.
breast carcinoma (16 papers, 2014 to 2025). "Differential allelic expression in the genomic region 4q21, in which gene ABRAXAS1 is located, has been previously reported to be associated with breast cancer susceptibility." (PMID 36703164, 2023). "Our screening efforts identified two truncating germline mutations in the gene encoding the BRCA1 complex partner ABRAXAS1 in German early-onset breast cancer patients." (PMID 37198153, 2023). "We studied DDRs in cells from heterozygous ABRAXAS1-mutation carriers to understand whether breast cancer-associated mutations in the gene encoding the BRCA1 complex partner ABRAXAS1 entail similar phenotypic changes as described for BRCA1-mutations." (PMID 37198153, 2023). "Yet, a case-control screening study of ABRAXAS1 missense and non-coding mutations in non-isolated populations of the Breast Cancer Family Registry did not reveal significant association with breast cancer risk." (PMID 37198153, 2023). "ABRAXAS1 germline variants have been described in Northern Finnish high-risk breast cancer families and in the germline of Non-Finnish cancer patients." (PMID 37198153, 2023).
cancer (10 papers, 2015 to 2025). A tumor composed of atypical neoplastic, often pleomorphic cells that invade other tissues. "In addition, ABRAXAS1 expression is reduced in various cancer entities and knockout mice exhibited decreased survival." (PMID 36551595, 2022). "Among the four associated genes without or very limited prior evidence in cancer pathophysiology is the single-gene locus spanning gene ABRAXAS1—a promising candidate gene for further follow-up owing to its close interactions with protein BRCA1 and its role in DNA damage repair." (PMID 36703164, 2023). "Moreover, new potential candidate genes emerged from complex sequencing studies of OC patients without being previously clearly established with any cancer, namely ABRAXAS1 (also known as FAM175A), CNKSR1, and PIK3C2G." (PMID 38069345, 2023).
tumor (6 papers, 2016 to 2025). "ABRAXAS1 is implicated in DNA repair and exerts tumour suppressive functions through its interactions with BRCA1." (PMID 39009827, 2024). "Remarkably, pathogenic variants in BRCA1/2 were present in patients both with and without clinical benefit, whereas variants in other known homologous recombination repair (HRR) genes were identified exclusively in tumor samples from patients with clinical benefit (ABRAXAS1, FANCA, and RAD51C)." (PMID 39591206, 2024).
ABRAXAS1 also shares sentences with these, for which no sentence is quoted: ovarian carcinoma (11 papers); breast and (1); cardiovascular disease (1); Fanconi anemia (1); glioma (1); hereditary cancer (1); lung adenocarcinoma (1); non-small cell lung carcinoma (1); pancreatic cancer (1); prostate carcinoma (1); triple-negative breast carcinoma (1).